LATS2 (large tumor suppressor kinase 2)
Diseases named in the same sentence as LATS2 in open-access papers (continued):
Sharing a sentence is not in itself a finding about the gene and the disease.
colon carcinoma (12 papers, 2013 to 2024). "Many tumor suppressors such as Deleted in Liver Cancer 1(DLC1) and Large tumor suppressor, homolog 2 (LATS2), downregulated in colon cancer cells, are upregulated followed by ERβ expression and targeted by miRNAs." (PMID 36207986, 2023). "The HPA atlas also showed that in colonic cancers, LATS2 methylation appeared to have a better prognosis (p = 0.018)." (PMID 34885067, 2021). "Accumulating evidence supports that the LATS family of human tumor suppressors (LATS1 and LATS2) is a new governor of cell homeostasis and LATS2 is downregulated in many cancers, such as prostate cancer and colon cancer." (PMID 31316723, 2019). "We proposed that the increased expressions of YAP/TAZ and their oncogenic function in colon cancer might due to the downregulation of LATS2 kinase by overexpressing of miR-429." (PMID 33414893, 2020). "And the study found that the transcription factor FOXC1 binding to the miR‐31 promoter increases the expression of miR‐31‐5p and regulates the expression of LATS2, leading to resistance to OXA in colon cancer cells." (PMID 39166861, 2024). "The expression of YAP, LATS2, Merlin and SAV1 genes were examined in both colon carcinoma cell lines." (PMID 37180710, 2023). "Likewise, Hippo kinases LATS1 and LATS2, the immediate downstream phospho-targets of STK3/4, were also shown to be essential for tumor cell growth in a colon cancer." (PMID 37345153, 2023). "MiR-373 is an oncogene and can induce tumor initiation and progression in testicular germ-cell tumors by targeting tumor suppressor LATS2, and invasion and metastasis by targeting CD44, RECK, mTOR and SIRT1 in breast, colon cancer and fibrosarcoma, respectively." (PMID 26258411, 2015).
prostate carcinoma (12 papers, 2014 to 2024). A carcinoma that arises from epithelial cells of the prostate gland. "LATS2 is abnormally expressed in numerous malignancies, including lung, breast, and prostate cancers." (PMID 35924072, 2022). "Guo and his colleagues reported that the occurrence of prostate cancer was related to the downregulation of LATS2 and the upregulation of YAP and miR-302/367 cluster." (PMID 33414893, 2020). "First, FOXP3 represses expression of the HER2, Skp2, SATB1 and MYC oncogenes, and induces expression of the tumor suppressor genes p21 and LATS2 in breast and prostate cancer cells." (PMID 24406338, 2014). "Furthermore, FOXO1, LATS2, and RB1 have been shown to act as tumor suppressor genes in various prostate cancer models." (PMID 38658552, 2024). "Knockdown of miR-302/367 inhibits tumorigenesis via regulating the LATS2/YAP pathway, suggesting that modulation of LATS2/YAP is critical for prostate cancer metastasis and resistance and, hence, targeting of this signaling axis may be of a great cancer therapeutic potential." (PMID 31530793, 2019). "FOXP3 has been shown to exert its growth inhibitory effect on breast and prostate cancer cells by transcriptionally repressing the expression of specific oncogenes (HER2, SKP2, SATB1 and MYC), and inducing the expression of specific tumor suppressor genes (CDKN1A, LATS2)." (PMID 24406338, 2014). "We noted that many Hippo pathway SNPs (one in MST1, three in STK3, two in LATS2, one in MOB1B, and six in WWTR1; total 13 out of 75) genotyped in our prostate cancer patient cohort were not in Hardy-Weinberg equilibrium (HWE)." (PMID 25707771, 2015).
astrocytoma (8 papers, 2010 to 2023). "In a series of 88 tumors, the percentage of tumors with downregulation of LATS1 and LATS2 due to promoter hypermethylation increased significantly from 48%/52% in grade 2 astrocytomas to 65%/70% in grade 3 astrocytomas and to 73%/82% in grade 4 glioblastomas." (PMID 37626776, 2023). "Hypermethylated promoter profiles were related to IDH mutation, yet not randomly in IDH-mutated gliomas, because LATS2 promoter hypermethylation was more frequent in oligodendroglioma than in astrocytoma." (PMID 33477668, 2021). "In addition, promoter hypermethylation mediates decreased expression of LATS1 and LATS2 in human astrocytoma." (PMID 26942001, 2016).
glioma (8 papers, 2020 to 2024). A benign or malignant brain and spinal cord tumor that arises from glial cells (astrocytes, oligodendrocytes, ependymal cells). "Compared with normal brain tissues, the expression levels of LATS1 and LATS2 are significantly decreased in glioma tissues and are associated with poor prognosis." (PMID 37423952, 2023). "Although LATS1/2 are considered as tumor suppressors, RASSF1/LATS2-coupled promoter hypermethylation was found to be associated with better overall survival in glioma patients." (PMID 33477668, 2021). "LATS2 deficiency, for instance, has been studied in several cancers including glioma." (PMID 33195240, 2020). "Further, WWP2 knockdown was found to enhance the stability of LATS2 protein in glioma cells, indicating the potential effect of WWP2 on the ubiquitination of LATS2 protein." (PMID 39166861, 2024). "CMTM5 regulated Hippo/YAP signaling to inhibit cell growth and invasion and to promote ferroptosis in glioma by regulating WWP2‐mediated LATS2 ubiquitination, thereby attenuating glioma progression." (PMID 39166861, 2024). "Another study revealed decreased expression of LATS2 in glioma tissues and cells, and LATS2 overexpression was found to suppress the growth of glioma cells." (PMID 39166861, 2024). "Future studies should aim to overcome the limitations of this study to explore the role of CMTM5/WWP2/LATS2 signaling in glioma." (PMID 39166861, 2024). "Erastin treatment promoted levels of Fe2+, lipid ROS, and MDA in glioma cells, which was abolished by LATS2 knockdown." (PMID 39166861, 2024). "Collectively, these findings indicate that CMTM5 inhibited WWP2‐mediated LATS2 ubiquitination in glioma cells." (PMID 39166861, 2024). "CMTM5 exerted a suppressive effect on cell growth and invasion and promoted ferroptosis of glioma cells by regulating the WWP2/LATS2 pathway." (PMID 39166861, 2024). "The TCGA Network project revealed that LATS2 is commonly hypermethylated in IDH-mutant low-grade gliomas, prompting us to explore its role in LGG." (PMID 33195240, 2020). "Here, we identified LATS2 as a substrate protein of WWP2 in glioma." (PMID 39166861, 2024). "In conclusion, we propose that CMTM5 may regulate Hippo/YAP axis to suppress cell growth and invasion and accelerate cell ferroptosis in glioma by inhibiting WWP2‐mediated LATS2 ubiquitination." (PMID 39166861, 2024). "This is the first study to demonstrate that CMTM5, which suppressed WWP2 expression through interacting with WWP2 protein, inhibited cell growth and promoted ferroptosis by attenuating WWP2‐mediated LATS2 ubiquitination and degradation, thereby alleviating glioma progression." (PMID 39166861, 2024). "Besides, LATS2 downregulation promoted cell viability, proliferation, migration, and invasion of glioma cells, whereas WWP2 knockdown or CMTM5 overexpression reversed these changes caused by LATS2 downregulation." (PMID 39166861, 2024). "For instance, LATS2 is negatively correlated with the outcome of patients with gliomas." (PMID 36118851, 2022). "Several groups have previously explored a role of LATS2 in gliomas." (PMID 33195240, 2020). "However, it is still unclear whether the CMTM5/WWP2/LATS2 axis is involved in angiogenesis in glioma and the treatment of glioma with bevacizumab." (PMID 39166861, 2024). "Therefore, we speculated that WWP2 might regulate Hippo/YAP signaling axis‐mediated glioma progression by mediating LATS2 ubiquitination." (PMID 39166861, 2024). "However, the underlying mechanism of low expression of LATS2 in glioma is not clear." (PMID 39166861, 2024). "Here, we found that WWP2 knockdown‐mediated reduction of WWP2 and YAP1 expression and elevation of LATS2 and p‐YAP1 levels in glioma cells was reversed by the combination of sh‐WWP2 and sh‐CMTM5 transfection." (PMID 39166861, 2024). "However, LATS2 knockdown‐mediated reduction of Fe2+, lipid ROS, and MDA levels in erastin‐induced glioma cells was reversed by WWP2 knockdown or CMTM5 overexpression." (PMID 39166861, 2024).
glioma (continued). "we did not investigate whether CMTM5/WWP2/LATS2 signaling affects DNA repair enzyme O6Meg DNA methyltransferase (MGMT) status in glioma." (PMID 39166861, 2024). "We found LATS2-methylated IDHmut-non-codel gliomas to be significantly enriched in young adults (FDR= 1.21E-13), while LATS2-methylated IDHmut-codel gliomas were suggestively enriched in later-onset cases (FDR = 0.100)." (PMID 34788626, 2021). "LATS2 knockdown promoted glioma cell viability, Erastin treatment suppressed cell viability and the variation tendencies of cell viability by sh‐LATS2/sh‐WWP2/oe‐CMTM5 transfection in erastin‐induced glioma cells mimicked those in glioma cells without erastin treatment." (PMID 39166861, 2024).
lung adenocarcinoma (8 papers, 2017 to 2024). A carcinoma that arises from the lung and is characterized by the presence of malignant glandular epithelial cells. "Clinically, co-expression of CADM1 and LATS2 on the cell membrane of cancer cells predicts good prognosis of lung adenocarcinoma." (PMID 32527032, 2020). "LATS2 mRNA expression in BLCA (urothelial bladder carcinoma), BRCA (invasive breast carcinoma), KICH (kidney chromophobe), LUAD (lung adenocarcinoma), LUSC (lung squamous cell carcinoma), and THCA (thyroid carcinoma) was lower than that in the normal tissues." (PMID 36118851, 2022). "To examine the importance of YAP/TAZ activation under EGFR in HNSCC and lung adenocarcinoma cells, we genome edited the LATS1 and LATS2 genes to activate YAP/TAZ in both cells harboring EGFR alterations." (PMID 34725466, 2021). "Notably, found that the lung adenocarcinoma cell exosome miR-19b-3p is regulated by YAP, the downstream core protein of LATS2 in the Hippo pathway." (PMID 38090595, 2023). "PVT1 recruited EZH2 to the large tumor suppressor kinase 2 (LATS2) promoter and repressed LATS2 transcription, and PVT1/EZH2/LATS2 interactions might serve as new target for lung adenocarcinoma diagnosis and therapy." (PMID 29046366, 2017).
pancreatic cancer (8 papers, 2013 to 2023). "MST1 or LATS2 silencing protected the apotosis induced by gemcitabine, and rendered pancreatic cancer cells to form more colonies in the presence of gemcitabine." (PMID 26561204, 2015). "Notably LATS2 was expressed more frequently in the healthy liver tissue compared to the pancreatic cancer cells within the liver parenchyma (< 0.01)." (PMID 33098447, 2021). "Thus, pancreatic cancer cells metastasizing to the liver versus ascites would have gone through very different adaptive processes and LATS2 stability regulation could be one of those mechanisms needing to be altered to fit different processes." (PMID 31659153, 2019). "In pancreatic cancer, miR-181-c is significantly upregulated, correlates with a worse prognosis, and represses the Hippo pathway by directly repressing LATS2, MOB1, MST1, and SAV1, promoting pancreatic cancer cell survival and chemoresistance." (PMID 34575852, 2021). "We then explored the functional significance of Hippo signaling in the chemoresistance of pancreatic cancer cells by silencing of the two key kinases MST1 and LATS2." (PMID 26561204, 2015). "Herein, we demonstrated that miR-181c was substantially overexpressed in pancreatic cancer and induced hyper-activation of YAP/TAZ via directly targeting MST1, LATS2, SAV1 and MOB1." (PMID 26561204, 2015). "Herein, we reported that miR-181c directly repressed MST1, LATS2, MOB1 and SAV1 expression in human pancreatic cancer cells." (PMID 26561204, 2015). "In summary, our study has revealed that miR-181c upregulation plays an important role in pancreatic cancer progression and miR-181c is a critical repressor of Hippo signaling by targeting the core kinase cassette, i.e., MST1, LATS2, SAV1 and MOB1." (PMID 26561204, 2015). "miR-181c directly repressed MST1, LATS2, MOB1 and SAV1, leading to YAP/TAZ activation and subsequent promotion of pancreatic cancer cell survival and chemoresistance in vitro and in vivo." (PMID 26561204, 2015). "The current study identified a novel ZIP4-CREB-miR-373 signalling axis that promotes pancreatic cancer growth, through silencing on key tumour suppressor molecules including TP53INP1, LATS2 and CD44." (PMID 23857777, 2013). "PR55α-knockdown results in an increase of LATS2 stability in CD18/HPAF but not in AsPC-1 pancreatic cancer cells." (PMID 31659153, 2019). "Therefore, repression of TP53INP1, LATS2 and CD44 revealed that each gene plays an important role in controlling pancreatic cancer growth." (PMID 23857777, 2013). "We found that silencing of TP53INP1, LATS2 and CD44 in MIA PaCa-2 cells significantly increased tumour growth compared with the vector control cells, indicating a bona fide tumour suppressor function in pancreatic cancer cells." (PMID 23857777, 2013). "In addition, this study provides a comprehensive mechanism for ZIP4-mediated pancreatic cancer growth involving CREB-dependent transcription, enhancement of oncogenic miR-373 expression, and reduction in key miR-373 regulated targets, including the tumour suppressor genes TP53INP1, LATS2 and CD44." (PMID 23857777, 2013).
testicular germ cell tumor (8 papers, 2008 to 2021). A germ cell tumor arising from the testis. "For example, miR372 and miR373 mediated silencing of LATS2 expression, a Hippo pathway tumor suppressor, is related with testicular germ cell tumors." (PMID 33892654, 2021). "MiR-372 can possibly directly inhibit the expression of the tumor-suppressor Lats2 to promote the development of human testicular germ cell tumors." (PMID 26673619, 2016). "The miR-372 and miR-373 miRNA cluster were originally associated with stemness in embryonic cells and oncogenicity in human testicular germ cell tumors via a concomitant targeting of LATS2 and CD44." (PMID 25714028, 2015). "It was then found that they act as oncogenes during the tumorigenesis of human testicular germ cell tumors by concomitant targeting of LATS2 and CD44 in order to overcome senescence and to promote metastasis, respectively." (PMID 25714028, 2015). "miR-372 and miR-373 were initially discovered as novel oncogenes participating in the development of human testicular germ cell tumors by targeting the cell cycle inhibitor LATS2." (PMID 22027184, 2011). "The present studies suggest that miRNAs might act as oncogene by targeting tumor suppressor genes, like miRNA-372, for instance, which can suppress LATS2 and induce testicular germ cell tumors." (PMID 29606985, 2018). "Thereby, as in the testicular germ cell tumors, abundant miR-372 and miR-373 in AGS cells, that totally silence LATS2, may participate in their active cell cycle progression despite high levels of p21cip1/waf1." (PMID 22027184, 2011).
esophageal squamous cell carcinoma (7 papers, 2017 to 2022). Esophageal squamous cell carcinoma (ESCC) is a type of esophageal carcinoma (EC) that can affect any part of the esophagus, but is usually located in the upper or middle third. "In esophageal squamous cell carcinoma, miR-31 was upregulated in clinical specimens and acted as an oncogenic miRNA by targeting the tumor suppressor gene LATS2, which is involved in the Hippo pathway." (PMID 34201353, 2021). "We carried out further research to assess the immune cell infiltration point of TCGA esophageal squamous cell carcinoma and found that samples with low LATS2 expression indicated large quantities of immune cells such as T-cell follicular helper M1 macrophages and myeloid dendritic cell resting." (PMID 36118851, 2022). "However, the correlation between LATS2 and esophageal squamous cell carcinoma (ESCC) and the association between LATS2 and immune infiltration in ESCC remain unclear." (PMID 36118851, 2022). "MiR-31 promotes EMT in esophageal squamous cell carcinoma through stimulating LATS2 expression." (PMID 32231464, 2020). "miR-373-3p targeting LATS2 and OXR1 enhances esophageal squamous cell carcinoma progression, and its expression was vigorously attenuated in the serum of patients with tumor resection." (PMID 34983307, 2022). "For example, it has been demonstrated that miR-135b regulates the Hippo pathway to promote lung cancer metastasis, and miR-31 inhibits the expression of LATS2 via the Hippo pathway and promotes epithelial-mesenchymal transition in esophageal squamous cell carcinoma (ESCC)." (PMID 33218358, 2020).
liver cancer (7 papers, 2018 to 2024). An epithelial or non-epithelial malignant neoplasm that arises from the liver. "For example, circ_0000140 inhibited the growth of oral squamous cell carcinoma cells through the miR-31/LATS2 axis, while circMTO1 impeded the proliferation of liver cancer cells through the miR-9/p21 axis." (PMID 38632984, 2024). "Indeed, the siRNA-mediated knockdown of LATS2 reduced the levels of phosphorylated YAP in 4 human liver cancer cell lines, proving that LATS2 negatively regulates YAP activity in liver cancer cell lines." (PMID 31540262, 2019). "LATS2 overexpression induces apoptotic cell death in SMMC-7721 and BeL-7404 liver cancer cell lines." (PMID 34577571, 2021). "It is reported that LATS2 suppression promoted EMT and cancer metastasis through enhancing mitochondrial ROS production in liver cancer." (PMID 33414893, 2020). "LATS2 overexpression and the activation of DRP1-related mitochondrial division via Wnt/β-catenin could open promising strategies to treat hepatocellular cancer by inducing cell viability downregulation, mitochondrial dysfunction, energy depletion, and apoptosis activation on liver cancer cells." (PMID 34577571, 2021).
osteosarcoma (7 papers, 2018 to 2025). A usually aggressive malignant bone-forming mesenchymal neoplasm, predominantly affecting adolescents and young adults. "In addition, in osteosarcoma, microRNA-744 accelerates osteosarcoma progression by inhibiting LATS2." (PMID 36118851, 2022). "The lncRNA HOTTIP (human homeobox A transcript) in osteosarcoma (OS) catalyzes LATS2 promoter methylation, inhibits LATS2 expression, activates YAP, initiates downstream target gene expression, and maintains OS cell viability, proliferation, migration, and invasion." (PMID 35071016, 2021). "CCAT2 overexpression promoted the LATS2 and c‐Myc expression in osteosarcoma cell." (PMID 29502343, 2018).
malignant mesothelioma (6 papers, 2015 to 2022). A malignant neoplasm of the pleura or peritoneum, arising from mesothelial cells. "NF2 and LATS2, the upstream components of Hippo pathway, are frequently observed to be inactivated in malignant mesothelioma (MM), leading YAP activation in more than 70% of analyzed primary MM tissues." (PMID 36398861, 2022). "Towards this goal we investigated YAP1 binding in NCI-H2052 malignant mesothelioma cells, a cell line of different lineage and with a different mechanism of YAP1 activation (NF2 mutation, LATS2 deletion)." (PMID 26295846, 2015). "A previous study further demonstrated that transduction of LATS2, a component of the Hippo signaling pathway, inhibited the oncoprotein YAP through phosphorylation, thus suppressing malignant mesothelioma cell growth." (PMID 32157157, 2020).